PORCN (porcupine O-acyltransferase)
Diseases named in the same sentence as PORCN in open-access papers (continued):
Sharing a sentence is not in itself a finding about the gene and the disease.
cholangiocarcinoma (1 paper, 2024). A carcinoma that arises from the intrahepatic biliary tree (intrahepatic cholangiocarcinoma) or from the junction, or adjacent to the junction, of the right and left hepatic ducts (hilar cholangiocarcinoma). "CGX1321, a PORCN inhibitor, has been tested in phase I clinical trials in patients with HCC and Cholangiocarcinomas (CCA) (NCT03507998)." (PMID 38634048, 2024).
developmental delay (1 paper, 2022). "We report two cases: one girl suffering from typical skin and skeletal abnormalities, developmental delay, microcephaly, thin corpus callosum, periventricular gliosis and drug-resistant epilepsy caused by a PORCN nonsense-mutation (c.283C > T, p.Arg95Ter)." (PMID 35101074, 2022).
esophageal adenocarcinoma (1 paper, 2025). A malignant tumor with glandular differentiation arising predominantly from Barrett mucosa in the lower third of the esophagus. "Inhibitors of porcupine O-acyltransferase (PORCN), including WNT974, have shown efficacy in preclinical models of esophageal adenocarcinoma, and their clinical evaluation in combination regimens is ongoing." (PMID 40649179, 2025).
head and neck cancer (1 paper, 2021). A primary or metastatic malignant neoplasm affecting the head and neck. "Selective porcupine (PORCN) inhibitors, LGK974 and ETC-159 target the secretion of Wnt ligands; these are being studied in ongoing phase 1/2 trials in metastatic colorectal and head and neck cancers." (PMID 33607955, 2021).
kidney cancer (1 paper, 2020). Primary or metastatic malignant neoplasm involving the kidney. "To investigate how PORCN affects kidney cancer, we selected the PORCN inhibitor LGK974 for experiments." (PMID 32104684, 2020). "Here we can basically determine that PORCN is involved in the development of kidney cancer as an oncogene." (PMID 32104684, 2020).
melanoma (1 paper, 2020). A malignant, usually aggressive tumor composed of atypical, neoplastic melanocytes. "The pharmacologic inhibition of protein-serine O-palmitoleoyltransferase porcupine (PORCN), an enzyme necessary for Wnt ligand secretion, synergistically suppressed melanoma progression when combined with anti–CTLA-4 antibody treatment." (PMID 33171792, 2020).
myelomeningocele (1 paper, 2020). Myelomeningocele is the most severe form of spina bifida. "In the Hispanic mutational burden comparison, the X chromosome gene PORCN associated with risk for myelomeningocele." (PMID 32970752, 2020). "Therefore, the likely deleterious variants found in PORCN in our MA myelomeningocele population may prevent WNT3A from leaving the endoplasmic reticulum, ultimately downregulating all WNT signaling pathways in the target cell because less WNT3A would be secreted." (PMID 32970752, 2020). "The genes PORCN, DVL2, CDH2, FUZ are already suspected to play a role in NTD development from studies in animal models and in some cases humans, however the remaining thirteen genes reported here are new in their possible association with myelomeningocele." (PMID 32970752, 2020). "Three myelomeningocele subjects (two females and one male) carried the three RDVs NC_000023.10:g.48371088G>A p.(Gly223Ser), NC_000023.10:g.48371104G>A p.(Arg228His), and NC_000023.10:g.48374165C>G p.(Ala336Gly), all in highly conserved functional regions of PORCN." (PMID 32970752, 2020).
Myocardial fibrosis (1 paper, 2022). "Moreover, in vivo and in vitro, blocking the Wnt signaling pathway with a PORCN inhibitor (WNT-974) could alleviate myocardial fibrosis and improve cardiac function." (PMID 36404310, 2022).
neuropathies (1 paper, 2023). "We expect similar, or even shorter, treatments with PORCN inhibitors will be sufficient to provide symptomatic relief for neuropathies." (PMID 37612291, 2023).
pancreatic IPMN (1 paper, 2022). "The Wnt/β‐catenin signaling pathway was activated in pancreatic KrasG12D and Rnf43 knockout mice and the PORCN inhibitor LGK974 blocked pancreatic IPMN initiation and progression to PDAC accordingly." (PMID 35229994, 2022).
renal carcinoma (1 paper, 2020). A carcinoma arising from the epithelium of the renal parenchyma or the renal pelvis. "We found that PORCN is highly expressed in renal cancer cell lines and patients with renal cell carcinoma with high expression of PORCN have a poor prognosis." (PMID 32104684, 2020). "We used real-time PCR to detect the expression of PORCN in four renal cancer cell lines 786-O, A498, ACHN, Caki, and normal renal epithelial cell lines HK-2." (PMID 32104684, 2020). "To explore the effects of inhibiting the two pathways on renal cancer, we have noted the PORCN gene." (PMID 32104684, 2020). "Then we analyzed the difference in survival between patients with high and low expression of PORCN in renal cancer patients by the Human Protein Atlas online tool." (PMID 32104684, 2020). "Taken together, we demonstrated that the expression of PORCN was upregulated in renal cancer cell lines." (PMID 32104684, 2020). "In conclusion, our results indicate that LGK974 could significantly inhibit the progression of renal cancer cells in a safe concentration range, so PORCN may be a safe and effective target for patients with renal cancer." (PMID 32104684, 2020). "We aimed at investigating the effects of PORCN inhibitor LGK974 on the biological behaviors of proliferation, apoptosis, migration, and invasion of renal cancer cells." (PMID 32104684, 2020). "In subsequent experiments, we found that PORCN inhibitor LGK974 killed renal cancer cells in a time- and concentration-dependent manner and inhibits renal cancer cell proliferation, induces apoptosis, and inhibits invasion and migration of renal cancer cells." (PMID 32104684, 2020).
renal cell carcinoma (1 paper, 2020). "In order to determine whether PORCN and its related genes have mutations in renal cell carcinoma, we conducted a study using the cBioportal online tool." (PMID 32104684, 2020). "The results showed that in addition to Wnt1 and Wnt2b, PORCN and other related genes have varying degrees of mutation in renal cell carcinoma, which may mean that PORCN and its related genes will play an important role in renal cell carcinoma." (PMID 32104684, 2020). "In order to explore the effect of PORCN inhibitor LGK974 on renal cell carcinoma, 786-O and ACHN cell lines were mainly used in our study." (PMID 32104684, 2020). "In this study, we used bioinformatics analysis and experimental verification to explore the role of PORCN in renal cell carcinoma." (PMID 32104684, 2020). "Although PORCN has been shown to play an important role in the secretion and activation of Wnt proteins, little is known about its role in renal cell carcinoma." (PMID 32104684, 2020). "Therefore, we have every reason to believe that PORCN can be used as an effective target to inhibit the occurrence and development of renal cell carcinoma." (PMID 32104684, 2020). "Although PORCN appears as an oncogene in other tumors, it is not known whether it is also an oncogene in renal cell carcinoma." (PMID 32104684, 2020).
sclerosteosis (1 paper, 2025). "Herein, using in vitro and in vivo approaches, we explore whether LGK974, another potent Wnt inhibitor that targets porcupine (PORCN, Wnt-specific acyltransferase), is a promising sclerosteosis therapeutic." (PMID 40189599, 2025). "This study also shows that PORCN inhibition may effectively limit characteristic HBM and skeletal overgrowth in sclerosteosis patients at sites with severe pathology." (PMID 40189599, 2025).
seminoma (1 paper, 2023). A radiosensitive malignant germ cell tumor found in the testis (especially undescended), and extragonadal sites (anterior mediastinum and pineal gland). "We treated GCT cell lines GCT44 and 1411H (YST), NTERA-2 (EC) and TCam2 (seminoma) with two different WNT inhibitors: the tankyrase inhibitor IWR-1 and the PORCN inhibitor LGK-974." (PMID 37149691, 2023).
thyroid cancer (1 paper, 2023). "Since thyroid cancer is rare among children and adolescents, we hypothesize that the PORCN pathogenic variant could be responsible for tumor susceptibility." (PMID 37859990, 2023).
X-linked dominant disease (1 paper, 2021). X-linked dominant form of disease. "FDH is an X-linked dominant disease and is due to mutations in the PORCN gene (Xp11.23), which encodes the porcupine O-acyltransferase, implicated in the secretion and signaling of WNT proteins, which are essential for embryonic tissue development." (PMID 34830686, 2021).
X-linked inherited disorder (1 paper, 2012). "Mutations in PORCN cause an X-linked inherited disorder called Focal Dermal Hypoplasia (FDH)." (PMID 22509316, 2012).
cancer (39 papers, 2012 to 2026). A tumor composed of atypical neoplastic, often pleomorphic cells that invade other tissues. "Published data suggest that upstream Wnt pathway inhibitors such as PORCN inhibitors are less effective in cancer cells with mutations of downstream Wnt pathway components such as APC mutations." (PMID 33923996, 2021). "Next, we assessed the combination of PORCN inhibitor and olaparib in three additional Wnt‐addicted cell lines from diverse cancer types with distinct Wnt pathway mutations." (PMID 33660437, 2021). "This vulnerability has offered an opportunity to treat human cancers that are genetically defined by RNF43 mutations with PORCN inhibitors." (PMID 32965059, 2020). "PORCN is located on the X chromosome and mutations on it can cause Goltz-Gorlin Syndrome55, but it has also been found to regulate a signaling pathway that controls cancer cell growth." (PMID 40021682, 2025). "PORCN is located on the X chromosome and mutations on it can cause Goltz-Gorlin Syndrome, but it has also been found to regulate a signaling pathway that controls cancer cell growth." (PMID 39132489, 2024). "In addition to the Wnt signaling pathway factors discussed earlier, other factors that inhibit or promote Wnt signaling pathway (such as RSPO, DKK1, PORCN) are also associated with a number of human cancers." (PMID 32486158, 2020). "However, similar to other cancer therapies targeting the Wnt pathway, skeletal side effects such as impairment of bone mass and strength and increase in bone resorption were caused by PORCN inhibitor administration." (PMID 32037398, 2020). "LGK974 (WNT974), a PORCN inhibitor, was reported to promote the remission of Wnt-related cancers in rats and was thus moved along for clinical testing in patients." (PMID 40607405, 2025). "Pharmacological inhibition of PORCN is highly selective for Wnt signalling and significantly inhibits the growth of Wnt-dependent tumours, highlighting its promise as a cancer therapy target." (PMID 40893937, 2025). "Pharmacologic targeting of PORCN blocks Wnt secretion and prevents the growth of Wnt ligand–dependent cancers." (PMID 38488003, 2024). "To identify Wnt-regulated genes and pathways, we examined the transcriptional response of multiple Wnt ligand–addicted cancer xenografts following PORCN inhibition." (PMID 38488003, 2024). "PORCN is required for the Wnt ligand secretion, and the inhibition of PORCN by LGK-974 is a promising strategy to target Wnt-driven cancers." (PMID 36896172, 2023). "It is possible that cancer cells were differentiated by PORCN inhibition‐induced suppression of Wnt signaling, as previously reported." (PMID 35040131, 2022). "Consistent with this, translational research indicates that PORCN inhibition is an effective therapeutic strategy against Wnt ligand‐dependent cancer." (PMID 35040131, 2022). "The suppression of Wnt signaling by PORCN inhibition is expected to serve as a differentiation therapy for genetically defined human cancers." (PMID 35836256, 2022). "Because of its requirement for Wnt signalling, PORCN is actively being pursued as a therapeutic target in Wnt-driven cancers." (PMID 34186010, 2021). "Although several studies have suggested that acylation mediated by PORCN is necessary for Wnt secretion, the latest findings in several cancer cells lines and a specific T cell seem to contradict that." (PMID 34722516, 2021). "PORCN inhibitors that block Wnt secretion have proven effective in Wnt‐addicted preclinical cancer models and are in clinical trials." (PMID 33660437, 2021). "Further, cells positive for pluripotency, stemness and cancer stem cell niche markers SOX2, ALDH1A1, EPCAM, LGR5 and PORCN were also significantly expanded in Ahr-deficient lesions along the time window analyzed." (PMID 34439225, 2021). "Inhibition of Wnt ligand secretion, namely through the inhibition of PORCN, has been under scrutiny during the last decade as a potential therapeutic approach for different types of cancer." (PMID 34367990, 2021).
cancer (continued). "PORCN is an acetyltransferase, important for maintaining the cancer stem cell niche, that participates in the secretion of proliferative factors that activate LGR5 such as, for example, Wnt." (PMID 34439225, 2021). "The PORCN inhibitor ETC‐159 has shown efficacy as a monotherapy in preclinical models of Wnt‐addicted cancers." (PMID 33660437, 2021). "In this study, we report that Wnt inhibition, via either PORCN or tankyrase inhibition, sensitizes diverse cancers to the PARP inhibitor olaparib." (PMID 33660437, 2021). "Currently, five small‐molecule PORCN inhibitors are evaluated in clinical trials for cancer treatment (ClinicalTrials.gov, NCT01351103, NCT02278133, NCT02521844, NCT03447470, NCT02675946, NCT03901950, and NCT03507998)." (PMID 32965059, 2020). "To investigate the role of PORCN in human ccRCC, we analyzed the expression of PORCN in 6 cancer tissues and adjacent tissues by immunohistochemistry." (PMID 32104684, 2020). "We found that more than 75% of the transcriptome responded to PORCN inhibition by ETC-159 in Wnt-addicted cancers, with significantly more genes changing in vivo than in vitro." (PMID 33092630, 2020). "PORCN inhibitors show promise for the suppression of Wnt signaling and for the treatment of various cancers by blocking the secretion and oligomerization of Wnt receptors." (PMID 31684152, 2019). "Blocking Wnt secretion by inhibiting PORCN enzymatic activity has shown efficacy in a subset of cancers with elevated Wnt signaling." (PMID 26848981, 2016). "Given the key roles of Wnt/β-catenin signaling in NPC, it is an attractive therapeutic approach to test PORCN inhibitor in this unique human cancer." (PMID 25980501, 2015). "We have discovered that PORCN knockdown affects cancer cell growth and tumorigenesis in a Wnt-independent manner." (PMID 22509316, 2012). "PORCN's Wnt-independent role in rapid proliferation has important implications for both embryonic development and cancer." (PMID 22509316, 2012). "ETC-159, an oral selective small molecule inhibitor of porcupine that inhibits Wnt protein (all members) secretion, is another PORCN inhibitor that has demonstrated significant anti-cancer effect in preclinical investigations and has thus been entered into phase 1 clinical trials." (PMID 40607405, 2025). "Consistent with the central role of Wnt signaling in regulating gene expression, inhibition of PORCN in cancers with RSPO3 translocation can lead to significant remodeling of the transcriptome, loss of cell cycle, stem cell and proliferation genes, and an increase in differentiation markers." (PMID 35836256, 2022). "Importantly, PORCN was shown to mark Wnt-producing tumor cells in a mouse model of LUAD that created a special microenvironment for Wnt-responding cancer cells." (PMID 34249925, 2021). "Importantly, our findings predict differential sensitivity of these RNF43 mutational classes to treatment with PORCN inhibitors, Wnt antagonists that are currently evaluated for clinical treatment of RNF43‐mutant cancer patients." (PMID 32965059, 2020). "Moreover, the inhibitor IWP-2 is proposed for the treatment of cancer, especially CRC due to RNF43 mutations, whereas PORCN inhibitors WNT974 and ETC-159 are applicable to cancer stem cells." (PMID 31684152, 2019). "Scientists are trialing cancer drugs that block a key enzyme PORCN and therefore inhibit Wnt signaling, but these drugs may also adversely affect patients’ bone structure." (PMID 29844946, 2018). "Interestingly, knockdown of PORCN in some cell lines produces a slow growth phenotype that is rescued by catalytically inactive PORCN, suggesting PORCN has additional functions in addition to acylation of Wnts in some cancer cells." (PMID 25208913, 2014). "This study is the first to implicate a Wnt-independent role of PORCN in cancer cells." (PMID 22509316, 2012).
cancer (continued). "Additionally, inducible PORCN knockdown by two independent shRNAs markedly reduces the growth of established MDA-MB-231 cancers in orthotopic xenografts in immunodeficient mice." (PMID 22509316, 2012). "In addition, PORCN inhibition was previously shown to block the anti-adipogenic and pro-osteoblastic effects of another agent used for cancer treatment, 5-Aza-dC,32 suggesting that adipogenic induction at the expense of osteoblastogenesis is a common effect of treatment with these agents." (PMID 29844946, 2018). "For example, male-amplified genes such as DLG3, PORCN, and PPFIA1 are involved in regulating postsynaptic membrane neurotransmitter receptor levels across multiple cancer types." (PMID 39716176, 2024). "Therapeutic agents like Porcupine (PORCN) inhibitors, WNT ligand antagonists, and frizzled (FZD) antagonists/monoclonal antibodies have been tested in clinical trials in various cancer types." (PMID 35646632, 2022). "During a screen to identify approved drugs that synergize with PORCN inhibitors, we made the unexpected observation that the PARP inhibitor olaparib synergized with ETC‐159 in Wnt‐addicted cancers." (PMID 33660437, 2021). "This subset of cancers is highly sensitive to upstream inhibitors of Wnt signaling pathway such as anti‐FZD and anti‐R‐spondin antibodies as well as PORCN inhibitors such as ETC‐159." (PMID 33660437, 2021). "We and others have demonstrated that PORCN inhibitors such as ETC-159 can effectively suppress Wnt signaling and the growth of Wnt-addicted cancers in multiple preclinical models." (PMID 33092630, 2020). "Current trials (NCT03447470 and NCT01351103) testing PORCN inhibition are limited to WNT-deregulated cancers and do not consider chemotherapy." (PMID 41117706, 2026). "However, up to date, there exist no DUB inhibitors that can be used for clinical purpose, whereas Wnt signaling inhibitors (such as WNT974, a PORCN inhibitor) are used in metastatic CRC and diverse human cancers." (PMID 32486158, 2020). "In this study we identify Notum as a potential biomarker for Wnt driven cancers and show that coordinate regulation of NOTUM and AXIN2 expression may be a useful predictor of response to PORCN inhibitors." (PMID 26848981, 2016). "PORCN protein thus appears to moonlight in a novel signaling pathway that is rate-limiting for cancer cell growth and tumorigenesis independent of its enzymatic function in Wnt biosynthesis and secretion." (PMID 22509316, 2012). "PORCN knockdown slowed cancer proliferation, unlike inhibition of PORCN enzymatic activity with the small molecule IWP-1." (PMID 22509316, 2012). "Previous studies indicated that Wnt-C59 did not significantly inhibit in vitro proliferation in 46 cancer cell lines at concentrations that might inhibit PORCN." (PMID 25980501, 2015).